ATM (ATM serine/threonine kinase)
Diseases named in the same sentence as ATM in open-access papers (continued):
Sharing a sentence is not in itself a finding about the gene and the disease.
cancer (continued). "Therefore, loss of function of ATM or RB1 protein may contribute to reduced DSB repair response and uncontrolled cell proliferation, which can lead to increased cancer susceptibility and vulnerability to radiotherapy or cytotoxic agents, e.g. cisplatin or carboplatin." (PMID 29682192, 2018). "The identification of new cytoplasmic signaling mediated by ATM in response to oxidative stress and the finding that ATM can regulate networks that ensure proteins and organelles quality open the question whether these networks may contribute to A-T pathogenesis and to cancer progression." (PMID 29616191, 2018). "It is possible that in these cancer cells, there is altered expression or activity of DSB signaling molecules such as ATM or ATR, which makes these cells particularly sensitive to VX-984-mediated DNA-PKcs inhibition." (PMID 29899825, 2018). "Over-expression of SALL1 significantly induced active, phosphorylated ATM in MCF-7, MDA and E0771 cancer cells." (PMID 29625565, 2018). "Across cancer lineages, we found that positive CTL score correlation with neoantigens and ATM protein levels to be largely mutually exclusive." (PMID 29615613, 2018). "To this end, by analyzing whole transcriptome and proteome data sets we identified phosphorylation of the DNA double-strand break response protein ATM as a novel potential driver of CTL invasion in breast and other C-class cancers." (PMID 29615613, 2018). "Investigation on cell cycle checkpoint signaling through ATM/ATR and pathways involved in cancer onset and progression has led to discover potent and selective ATM/ATR inhibitors that are actually in preclinical and clinical development, respectively." (PMID 29770165, 2018). "Therefore, controlled targeted inhibition of the DDR factors such as ATM, checkpoint kinases and DNA-PK, combined with chemotherapeutic drugs would represent a useful strategy to prevent temporary cell cycle arrest and DNA damage repair, to promote cancer cell death and to improve patient outcome." (PMID 28587121, 2017). "Here, we demonstrate that CC-115 is a selective mTOR kinase/DNA-PK dual inhibitor with excellent kinase selectivity, even over closely related ATR, ATM and PI3K-alpha and with potent inhibitory activity across many cancer cell lines." (PMID 29088817, 2017). "Together, these data suggest the important role of ATM in the production of dNTPs and NADPH in the proliferation of cancer cells and protection against ROS." (PMID 29238697, 2017). "Recently, increasing evidences have confirmed that miR-210 functions as an oncogene in many types of cancers by degrading its targets such as E2F3, Casp8ap2 and ATM." (PMID 28415557, 2017). "The ability of cancer cells to sense ROS through ATM and reprogram metabolism by increasing PPP activity allows for cancer cell survival and resistance to therapy." (PMID 29238697, 2017). "Using Western blot, we found that cell-cycle associated factors were upregulated in the group A antigen-expressing 231-A6 cancer cells, including Cyclin D, Cyclin E, CDK2, CDK6, E2F, and ATM." (PMID 28122343, 2017). "The key role held by ATM in maintaining genomic integrity as part of the DDR suggests that early loss of ATM function in the process of malignant transformation could herald the generation of a mutator phenotype, an “enabling feature” in the evolution of cancer." (PMID 28418844, 2017). "Interesting targets to overcome these cancer defense mechanisms are: PARP, DNA-PK, PI3K, ATM, ATR, CHK1/2, and WEE1 inhibitors." (PMID 29113422, 2017). "Nevertheless, these data support the notion that ATM regulates the PPP to affect dNTP synthesis and NADPH production in cancer cells." (PMID 29238697, 2017). "In present study we present a novel function of excess Cdc7-Db4 in overriding replication stress to promote cancer cell survival and tumorigenesis by the phosphorylation of HSP90-S164 that enhances the ATR/ATM-mediated signaling and HR DNA repair." (PMID 29209046, 2017).
cancer (continued). "Overexpression of Aurora B mRNA and protein has been detected in a number of cancers, and tumorigenic changes have also been observed for the WNT and ATM pathways." (PMID 28498803, 2017). "Consistently, pharmacological inhibition of ATM inhibits AKT phosphorylation and survival in multiple cancer types." (PMID 29238697, 2017). "In summary, our study identifies RanBP9 as a new target of ATM, critically involved in the prompt activation of DDR signaling, repair of damaged DNA and cancer cell sensitivity to genotoxic stress." (PMID 26943034, 2016). "A challenge ahead will be to gain insight into mechanisms of NSE repression in normal and cancer cells where the NSE control appears to be compromised, potentially altering ATM expression and DDR in the haplotype-dependent manner." (PMID 26732650, 2016). "Thus in rapidly dividing cancer cells Chk2 may become activated in an ATM-independent manner." (PMID 27121056, 2016). "Nonetheless, several gene sets with potential importance for cancer development are enriched such as genes positively correlated with BRCA1, ATM, and CHEK2 expression across normal tissues (GSEA, q < 10-28)." (PMID 25768983, 2015). "In fact, Weber and Ryan suggested that ATM and ATR can serve as therapeutic targets either as a monotherapy in cancers with DDR defects, or as a combinatorial therapy in other relevant cancers." (PMID 26404381, 2015). "It is worth noting that although LOH in cases with BRCA1 and BRCA2 truncations mutations were largely restricted to OV and BRCA, the majority of LOH truncations in other genes (for example, ATM, PALB2, BAP1, FANCM) were found across cancer types." (PMID 26689913, 2015). "Analysis of individual cancer types revealed significant early onset for germline truncations of FANCA in HNSC, BRIP1 in LUSC and ATM in STAD." (PMID 26689913, 2015). "Contrary to the function of CHMP4C on cell fate, inhibition of ATM enhances ARF levels and stimulates the tumor-suppressive effects of ARF in human oncogene-transformed and cancer cells." (PMID 26712741, 2015). "Therefore, the observation that dampening Tel1/ATM signaling activity restores DNA damage resistance in sae2Δ cells might have implications in cancer therapies that use ATM inhibitors for synthetic lethal approaches to threat tumors with deficiencies in the DNA damage response." (PMID 26584331, 2015). "The inhibition of ATM function has therefore been proposed, similarly to the inhibition of other DDR components, as a valuable mechanism to overcome cancer cell resistance to IR or to chemotherapy." (PMID 24681585, 2014). "We choose two ATM-ATR inhibitors, that is, caffeine and KU-55933, and pretreated cancer cells with these inhibitors prior to administering ionizing radiation or HDAC inhibitors." (PMID 24512718, 2014).
cancer (continued). "Considering the ATM and ARF interplay in carcinogenesis, we discuss in this article the role of ARF at the crossroads of cancer and developmental processes." (PMID 25101116, 2014). "The data is entirely consistent with pre-clinical studies demonstrating an essential role for ATM, DNA-PKcs and ATR in determining platinum sensitivity in cancer cell line models." (PMID 26674120, 2014). "ATM and CASP8 disproportionately increase in relative instability (compared to the other 48 genes in the deletion-prone cancer gene group) as the fraction of deletions ≤50 bp was increased." (PMID 23755193, 2013). "Some of the most paradigmatic examples of cancer genes such as BRCA1, BRCA2, NF1, and ATM are included in these two sets." (PMID 24204383, 2013). "Further studies are needed to elucidate the relationships among MAGE proteins, Smc5/6 components, and proteins such as ATM and ATR that are also important for resistance to genotoxic agents in normal and cancer cells." (PMID 23555814, 2013). "The central roles of ATM and ATR in genome maintenance suggest the potential to manipulate their activity for cancer chemotherapy, fueling the development of potent small molecules that specifically inhibit ATM and ATR activities in cellulo." (PMID 23592994, 2013). "Further studies will allow to deeply evaluate whether and in which contexts ATM expression and activity may represent a marker to predict the efficacy of chemotherapy agents as valuable approaches for combined strategies to enhance cancer cell sensitivity to TRAIL." (PMID 24213315, 2012). "Image cytometry was performed on 469 of the 908 cancers: for γ-H2AX, 385 tumours with both IHC and ploidy analysis were successfully analysed; for ATM, 394 tumours were studied; and for Ku70, 204 tumours were analysed." (PMID 23154512, 2012). "These opposing effects on cancer progression are controlled by two different branches of DDR signaling, respectively ATM/CHK2 and ATR/CHK1." (PMID 22373487, 2012). "Inhibiting ATM, ATR or their downstream targets thus serves to widen the therapeutic window of genotoxic anti-cancer therapeutics by sensitizing cancer cells to these agents (reviewed)." (PMID 19903334, 2009). "In this study, we have observed that in contrast to the ATM selective inhibitor KU55933, ATM/ATR dual inhibitors such as caffeine and CGK733 can suppress cyclin D1 levels in cancer cell lines." (PMID 19903334, 2009). "These and other data indicate that early in tumorigenesis, before malignant conversion, human cells activate the ATM- and ATR-dependent DNA damage response, which delays or prevents cancer." (PMID 18577246, 2008).
cancer (continued). "These include a number of known or potential tumour suppressor genes (BCSC-1, CHEK1, ST14, ATM, P53AIP1), genes with proposed roles in cancer progression (BARX2), apoptosis (PIG8, P53AIP1) and oncogenesis (FLI1, ETS1), and a DNA damage-inducible gene (DDI1)." (PMID 18506147, 2008). "Gaining deeper insights into ATM’s relationship with mTOR and PI3K/Akt signaling pathways could support the use of pathway inhibitors in cancer therapy." (PMID 41557625, 2026). "Also, ATM, ATR, and TP-53 genes were downregulated with NaB treatment in COLO-205 cancer cell lines." (PMID 40872562, 2025). "The decrease in mTORC1 activity upon ATR inhibition, but not ATM inhibition, in another cancer cell line (HeLa) was also rescued by supplementation with cholesterol (Fig. EV4A,B)." (PMID 40514450, 2025). "Indeed, many cancers are often reliant on these proteins for continued proliferation, and ATR and ATM inhibitors are in clinical trials for a variety of malignancies." (PMID 40514450, 2025). "Further studies distinguishing 5mC levels from other cancer patients without ATM defects are required." (PMID 39812834, 2025). "Many cancers exhibit defects in DDR, making them more reliant on ATR/Chk1 or ATM/Chk2 for survival." (PMID 40422251, 2025). "This cellular mechanism also clarifies why miRNA patterns observed in ATM-low cancer tumor cells do not directly correlate with complete ATM-null A-T cells." (PMID 41065894, 2025). "Targeting of the DNA repair pathways in cancer alone is also of high interest, as cancers are characteristically genetically unstable and generally have impaired DNA repair (e.g., BRCA and ATM mutants) and thus rely more heavily on alternative repair pathways to survive during chemotherapy." (PMID 39617061, 2025). "Additionally, radiation has been shown to downregulate the expression of SLC7A11 in cancer cells in an ATM-dependent manner, leading to a reduction of cystine uptake and GSH synthesis, ultimately inducing ferroptosis in cancer cells." (PMID 40482348, 2025). "We therefore selected 3 cell lines encoding BRCA1 (UWB1.89 and HCC1937) or ATM (H1395) mutations, with non-mutated SKOV3, MCF-7 and A549 cell lines as cancer-type matched controls." (PMID 39994444, 2025). "At present, the commonly used method to treat cancer is to activate the cancer cell cycle checkpoints such as ATM, ATR, CHK and other genes, so that cancer cells can die normally." (PMID 39944835, 2025). "ATM inhibitors enhance the anticancer activity of DNA damage agents such as topoisomerase inhibitors1260 and PARP inhibitor.1261 Collectively, ATM-targeted therapy has a promising potential in cancer therapy." (PMID 38763973, 2024). "Importantly, short treatments with ATM and ATR inhibitors in cultured cells increased the levels of cancer-specific rearrangements." (PMID 38773641, 2024). "Given the remarkable therapeutic effects in treating cancer, it is somewhat unexpected that ATM inhibitors have not been widely used in clinical." (PMID 38671157, 2024). "If the nucleoshuttling of the ATM protein is not performed in due time (some minutes), toxicity, cancer or accelerated aging is observed." (PMID 38893223, 2024). "This led us to unravel that ATM and ATR inhibitors represent a strategy particularly suited to jeopardize DDR in acid-exposed cancer cells and exert growth inhibitory effects on this aggressive tumor compartment either as a single agent or in combination with chemotherapy." (PMID 38366255, 2024).
cancer (continued). "Therefore, ATM and ATR inhibitors are also used in cancer therapy to treat patients with ALT-positive cancers." (PMID 38910895, 2024). "Synthetic lethal approaches being investigated in tumor-agnostic studies include PARP inhibitors for BRCA1/2- or ATM-mutant cancers; ATR inhibitors for ATM-mutant cancers; and PKMYT1 inhibition for solid tumors with CCNE1 amplification, FBXW7 loss, and PPP2R1A mutations (NCT04855656)." (PMID 38938274, 2024). "Interestingly, E7820-mediated double-strand breaks in DNA were increased in tumors with BRCA2 dysfunction, and knockdown of BRCA1/2 transcripts or knockout of ATM, ATR, or BAP1 sensitized cancer cells to E7820." (PMID 38789724, 2024). "Several clinical trials of ATM inhibitors are ongoing, but only one Phase I trial has concluded, studying the safety and preliminary efficacy of AZD0156 alone or in combination with other anticancer treatments in patients with advanced cancer." (PMID 39033176, 2024). "ATM and ATR inhibitors can also be used for the treatment of ALT-positive cancers." (PMID 38910895, 2024). "Our phosphoproteomic analysis followed by a validation study revealed alterations in the signaling networks and identified radiosensitizing molecular targets, including HDAC, ATM, and p38, in response to TAT with a 225Ac-labeled minigastrin analog in CCKBR-positive cancer cells." (PMID 36732057, 2023). "Indeed, we found that inhibition of ATM led to a robust increase in the expression of cGAS, the phosphorylation of STING and TBK1 in a variety of human cancer cell lines, including HeLa, H157, H1299, A549, MDA-MB-231 and BT549." (PMID 36778120, 2023). "In addition to BRCA1 and BRCA2, many other HRR mediators (ATM, BRIP1, CHEK2, NBS1 or RAD51C) are frequently defective in cancer." (PMID 37298484, 2023). "The remaining most frequent mutated cancer driver genes found in early-stage samples (KMT2C, ALK, BRCA2, GRM, ATM, and BRCA1) were not among those found to be the most frequently shared in late-stage samples (MUC16, CSMD3, KNT2C, NF1, LRP1B, SPEN, and TRRAP)." (PMID 37446001, 2023). "Similarly, inhibitors targeting DDR-related genes, such as DNA-dependent protein kinase, catalytic subunit, ATM, ataxia telangiectasia and Rad3-related protein, CHK1, and WEE1, exhibit promising anti-cancer effects." (PMID 37448962, 2023). "They suppress ATM catalytic activity in cancer cells and animal models and have shown strong potentiation of the antitumor activity of ionizing radiation and DSB-inducing chemotherapeutic agents offering possible new combination partners for cancer therapy." (PMID 36656721, 2023). "Further analysis should be done to check the role of ATM in the radiation response of cancer and non-malignant cell lines." (PMID 36229655, 2023). "As regards ATM exon 29 deletion, no research has been reported so far about the same deletion in cancer." (PMID 37628581, 2023). "ATM inhibitors can induce interferon responses and have the potential to enhance the efficacy of ICB therapy in cancer patients, including those with cisplatin-refractory cancers." (PMID 37174688, 2023). "This is also the first report demonstrating the association of MRE11 rs2155209, XRCC5 rs828907, LIG4 rs1805388, ATM rs1801516 and RAD51 rs12593359 with survival in HNSCC, as well as the first to indicate that CHEK1 rs558351 may play a role in cancer disease." (PMID 37894339, 2023). "There are several reports on ATM gene association and functional mechanisms in the DDR, homologous recombination repair (HRR), and the non-homologous end joining pathway in cancer." (PMID 37020276, 2023). "For this reason, ATM inhibitors have been developed for use in cancer therapy and have been reported less harmful for non-tumoral cells." (PMID 36672401, 2023).